CD4 (CD4 molecule)
Diseases named in the same sentence as CD4 in open-access papers (continued):
Sharing a sentence is not in itself a finding about the gene and the disease.
tumor (continued). "The number of EM CD4 and CD8 T cells increased substantially, suggesting a heightened presence of T cells primed for immediate immune responses against the tumor." (PMID 39218928, 2024). "Chemotherapeutic treatment of tumor-bearing mice was reported to lead to intratumoral expression of CXCL9, CXCL10, and CCL5 chemokines which facilitate recruitment and infiltration of CD4+ and CD8+ T cells into the tumor bed." (PMID 38360737, 2024). "Immunohistochemistry (IHC) staining also confirmed increased CD4+ and CD8+ T cells in the tumor tissues of vaccinated mice compared with control tumor tissue." (PMID 38298111, 2024). "The immunized animals showed decreased CD4 + FoxP3 + T cells, increased interferon (IFN)-γ and IL-17a levels, enhanced KRAS-specific Th1 and Th17 responses, and significantly reduced tumor incidence compared to controls." (PMID 39204073, 2024). "The infused allografts during HCT contain mature CD4+ and CD8+ αβ T cells which establish hematopoietic engraftment, reconstitute T cells immunity, and induce graft-vs.-tumor (GVT) effect that is key for elimination of the malignant cells." (PMID 38993780, 2024). "The expression of GSDMD was significantly and positively correlated with the GSDMD expression was significantly and positively correlated with the tumor purity of LIHC and the degree of infiltration of CD4+ T cells." (PMID 38434972, 2024). "As expected, both CD4+ T cells and CD8+ T cells were significantly enriched in tumor tissue from mice treated with LLCvac (p = 0.0196 and p = 0.0071)." (PMID 38280084, 2024). "In contrast, expression of CD39 was found on antigen-specific (tumor-infiltrating) CD8+ T cells, con CD4+, and reg CD4+ T cells." (PMID 39518969, 2024). "Nevertheless, CD8+ and CD4+ cells’ tumor infiltration was enhanced dramatically after the depletion of Wdr5, which is consistent with elevated CD8/CD4 expression in RNA level." (PMID 39201460, 2024). "This targeted delivery mechanism aids in activating CD4/CD8+ T cells, disrupting the inhibitory TME, and bolstering the anti-tumor immunity cycle." (PMID 38998669, 2024). "We discovered that FAM20A expression inversely correlates with tumor purity in LUSC, and positively correlates with the presence of B cells, CD8+ T cells, CD4+ T cells, macrophages, neutrophils, and dendritic cells." (PMID 38983866, 2024). "CD160, a glycosylphosphatidylinositol-anchored Ig domain protein that is expressed on NK cells, γδ T cells and a minor subset of CD4+ and CD8+ T cells, is also overexpressed in some ESCC tumours in our study." (PMID 39419971, 2024). "Studies in human cancer have demonstrated the formation of clusters or ‘triads’ comprising T cells (CD4+ and CD8+) alongside DCs within the tumor and found both in dLN and the TIME." (PMID 38716077, 2024). "The major cellular sources of IL-10 are CD4+ T cells, CD8+ T cells, a subset of Tregs and tumor cells." (PMID 39235457, 2024). "CD4, CD25, and FOXP3 are essential for the development, maturation and functioning of Tregs and provide a suitable microenvironment facilitating tumor escape." (PMID 39264227, 2024). "Careful antigen peptide selection and inclusion of both MHC class I and II epitopes can elicit coordinated CD4+ and CD8+ T-cell responses for optimal anti-tumor immunity." (PMID 38785789, 2024). "Subsequently, the immunofluorescence staining of tumor‐infiltrating helper T lymphocytes (HTLs, CD3+CD4+) and cytotoxic T lymphocytes (CTLs, CD3+CD8+) was performed to further demonstrate the antitumor immune response." (PMID 39494618, 2024). "In comparison, most CD4/CD8+ T cells were concentrated at the tumour boundaries, with fewer cells infiltrating the tumour bed in PBS‐treated tumours." (PMID 39390760, 2024). "DCs possess the capability to capture antigens generated and released during tumorigenesis, subsequently presenting tumor antigens to naive CD8+ T and CD4+ T cells through major histocompatibility complex (MHC)-I and MHC-II molecules." (PMID 38816455, 2024).
tumor (continued). "The expression of αvβ8 was highest in CD4+CD25+ T cells within tumors and deleting β8 specifically from T cells proved as effective as ADWA-11 in inhibiting tumor growth." (PMID 38675493, 2024). "It has also been shown that patients with PMs have increased frequencies of CD4+ memory T cells which express the checkpoint receptors PD-1, VISTA, and TIGIT in the omental fat when compared to patients with only a primary CRC tumor." (PMID 38384469, 2024). "SIGLEC-E, an SIGLEC7/9 analog, was overexpressed in CD4+ and CD8+ tumor-infiltrating T cells, and its levels were also dependent on sialyltransferase activity." (PMID 39727942, 2024). "The cytokines and chemokines in the TME engineer the pro- and anti-tumorigenic activities and thereby guide the MDSCs and Tregs to obstruct tumor immunity, while NKs, CD8+, CD4+ T cells, M1 macrophages, and DCs to stimulate an antitumor response." (PMID 39201585, 2024). "Furthermore, H. hepaticus gut colonization induced the development of H. hepaticus-specific CD4+ T follicular helper cells in colorectal tumors, which drove the formation of tertiary lymphoid structures in the colonic lamina propria and controlled the tumor growth." (PMID 39120310, 2024). "Prolonged immunotherapy can elevate PD-1 expression in CD4+ and CD8+ T cells, leading to reduced infiltration of these cells into the tumor and decreased levels of activation markers such as IFNγ, TNFα, and granzyme B." (PMID 38927907, 2024). "The in vivo experimentation, involving immunocompromised NSG mice and xenogeneic T cell graft, displays a valuable result regarding the differential capacity of CD4+, CD8+ and total TCR-T to control tumor growth." (PMID 38545119, 2024). "CXCL9/10/11 do not only recruit effector CD4+ and CD8+ to tumor sites but also inflammatory sites in the body." (PMID 38928238, 2024). "These include CD3+PD-1+, CD4+PD-1+, CD8+PD-1+, CD4/CD8, LYM%, MON%, WBC, NLR, MLR, ΔCEA%, CYFRA21-1, LDH, tumor types and age." (PMID 38451413, 2024). "A decrease in CD4+ regulatory T cells and an increase in IL-2, CCL-5 and IFN-γ production, as well as CD8+ T cell infiltration, proved anti-tumor effect." (PMID 38778925, 2024). "This alteration in the TIME is characterized by a rise in tumor-killing cells including interferon (IFN)γ+ CD8, NK, and NKT-cells, accompanied by a reduction in MDSCs and PD-1hi CD4 T-cells, ultimately reversing the immune-suppressive TME." (PMID 38331927, 2024). "In particular, the balance between CD4+ and CD8+ T cell subsets is vital in shaping the anti-tumor immune environment." (PMID 39459546, 2024). "In the context of HCC, the initial stages of the disease witness a notable increase in both circulating and tumor-infiltrating CD8+ and CD4+ T cells, which subsequently decline as the disease advances." (PMID 38791916, 2024). "Compared with healthy controls, anti-tumour T cell function was impaired in OAC patients, demonstrated by lower IFN-γ production by CD4+ T helper cells and lower CD8+ T cell cytotoxic potential." (PMID 38672174, 2024). "Research has consistently shown a significant relationship between CD4+ T cell infiltration and TNBC, with CD4+ T cells playing crucial roles in modulating tumor progression and shaping the immune response." (PMID 39769460, 2024). "The PD-1 receptor, belonging to the CD28 family, is present on B lymphocytes, CD4+ and CD8+ T lymphocytes, natural killer (NK) cells, monocytes and activated dendritic cells and is responsible for inhibiting the anti-tumor response." (PMID 38397167, 2024). "We also monitored the presence of endogenous CD4+ cells in immune cell-enriched lymphatic organs, such as the spleen and lymph nodes, and in the TME of tumor-bearing WT and hCD4-KI mice." (PMID 39239511, 2024). "The first panel featured staining for tumor cells (pan-CK+), B cells (CD20+), CD4+ and CD8+ T cells, Tregs (CD4+FOXP3+), and macrophages (CD68+)." (PMID 38994676, 2024).
tumor (continued). "We see clustering of B cells, Tregs, and CD4+ T cells near the tumor in PDCA13 with distinct CD8+ T cell exclusion, while PDCA12 shows a B cell, macrophage, and CD4 clustering, which is less tumor proximal." (PMID 38968363, 2024). "The high expression of YAP1 in tumor tissue can lead to the depletion of CD8+T and CD4+T cells, facilitating the proliferation and dissemination of liver tumor cells." (PMID 38550587, 2024). "Similar effects on tumor infiltration of both MDSC populations, effector CD4+ T cells, CD4+ Tregs, and NK cells were observed in MC38 B2m KO tumors." (PMID 38427670, 2024). "Further, animals treated with rAd5-16/E6E7Wt had increased CD4+ and CD8+ tumor-infiltrating lymphocytes (TILs) and produced a cytotoxic tumor microenvironment." (PMID 39339987, 2024). "CD4+ T cells alter tumor metabolism leading to enhanced TNF-α-dependent oxidative stress and tumor cell death." (PMID 39068665, 2024). "Conversely, lymphocytes induce tumor cell death, inhibit proliferation and migration, primarily mediated by CD8+ and CD4+ T cell interactions, releasing cytotoxic mediators and cytokines." (PMID 39267826, 2024). "Foxp3+ regulatory T cells (Tregs), a CD4+ T cell subset, play a role in inhibiting CD8+ and CD4+ cells in the TME, restricting anti‐tumor immunity through downregulation of effector T cell induction and proliferation." (PMID 39240588, 2024). "Immune cell infiltration within tumor tissues was assessed using flow cytometry, with results displaying that the levels of CD3, CD4, and CD8 immune cells within the tumor tissues were notably elevated in both group PD-L1 and group Prevotellaceae." (PMID 39641253, 2024). "For this reason, we are obliged to use LVs that will exclusively transduce the CD8 + tumor infiltrating T cells in order to avoid CAR T cell fratricide and CAR expression by their counterpart malignant CD4 T cells." (PMID 39272178, 2024). "Enhanced cytotoxicity of CD4+ and CD8+ T cells in vaccinated mice is verified in co‐culture with tumor cells." (PMID 38298111, 2024). "Small molecule AKT activator, SC79, impaired the growth of poor immunotherapy responder murine tumours, B16 and EMT-6 suppressing CD4+Foxp3+Treg TILs through the conversion of Tregs to IFNγ+CD4+Th1-like T cells." (PMID 38704478, 2024). "CD4+ T cell depletion and, to a smaller extent, CD8+ T cell depletion resulted in tumour formation in poly(I:C)-treated sites." (PMID 38472944, 2024). "These tumor-derived components also contribute to an immunosuppressive microenvironment by promoting the secretion of VEGF in monocytes, Tregs, B cells, and CD4 naive T cells." (PMID 38348038, 2024). "In a comparable retrospective study, a positive impact on prognosis was demonstrated by a dense infiltration of CD4 + T cells and CD8 + T cells in the tumor stroma of NSCLC24." (PMID 38902361, 2024). "In our previous studies, we demonstrated that Th1 cells are the dominant in subset of CD4+ T cells at the late stage after CTT and mediate long-term anti-tumor immunity." (PMID 38791188, 2024). "Following priming of the mice with male cells, there were accumulation and expansion of both Tg CD4 and CD8 T cells, which were considered bystander, into the tumor and tumor-draining lymph nodes." (PMID 39669576, 2024). "The tumor antigen-binding scFv facilitates specific targeting of tumor cells and activates the TCR-mediated cytotoxicity via the CD4 co-receptor domain." (PMID 38904025, 2024). "These peptides can be engulfed and presented by APCs to autologous CD4+ and CD8+ T cells after in vivo administration and then circulate to the tumor site, where they exhibit cytotoxicity." (PMID 39406966, 2024). "Through IHC, we evaluated the expression levels of CD3, CD4, CD8, as well as PD-L1 (both tumor proportion score (TPS) and combined positive score (CPS))." (PMID 39231924, 2024).
tumor (continued). "Several studies have shown that the combination of bevacizumab with ICIs significantly increases the infiltration of CD4 and CD8+ T lymphocytes within the tumor microenvironment." (PMID 38280084, 2024). "This was associated with an increase in activated PD-1+ tumor-infiltrating Tregs and suppression of CD4+Foxp3− and CD8+ T cells in tumor tissues." (PMID 38672681, 2024). "Biologically, T cells contain many sub-types, including CD4+, CD8+, regulatory T cells, and more, and their functions are diverse in the tumor microenvironment." (PMID 38741183, 2024). "At the same time, the proportion of CD4+ T cell subsets in the spleen and the frequency of CD8+ T cells in distal unirradiated tumor‐draining lymph nodes also increased." (PMID 38911063, 2024). "IHC revealed that treatment with the STING agonists increased infiltration of CD3+ T cells, CD4+ Th cells, and CD8+ cytotoxic T cells, as well as PD-1–expressing cells, into the tumor." (PMID 38502231, 2024). "Blood and tumor tissue-based flow cytometric phenotyping reveals an increase in effector memory CD8 and CD4 T cells and a decrease in immunosuppressive cells accompanied by a significant increase in IL-2, IFN-γ, and GM-CSF levels in the combination group." (PMID 39218928, 2024). "CD4 + T and CD8 + T cells constitute major components of tumor-infiltrating lymphocytes (TIL) and play different roles in antitumor immunity; they also consist of different cell subtypes." (PMID 38468248, 2024). "Higher prevalence of Meflin-positive CAFs is positively correlated with CD4-positive T-cell infiltration and vascularisation within NSCLC tumour." (PMID 38352889, 2024). "The beneficial effect of anti-PD-1 antibodies reflects the robust activation of IFN-γ-secreting CD4+ and CD8+ T cells by NanoST because IFN-γ induces the expression of PD-L1 on tumor cells." (PMID 39152131, 2024). "While cDC1 primarily drives CD8+ cytotoxic T-lymphocytes (CTL) responses and cDC2 activates CD4+ T-lymphocytes within the TME, inadequate DC recruitment under tumor growth conditions hampers anti-tumor immunity." (PMID 38954010, 2024). "In vivo, CD4+ T cells co-expressing CAR T cells unique to B7H6 mouse tumors and overexpressing T-bet promoted anti-tumor responses and lengthened the survival of RMA-B7H6 lymphoma-bearing mice." (PMID 38328405, 2023). "In biologically old patients, a lower infiltration of CD163+ macrophages (p = 0.036) as well as CD4+ (p = 0.019) and CD8+ (p = 0.026) lymphocytes was found in the tumor microenvironment." (PMID 37568649, 2023). "Altogether, these results indicate that during progressive outgrowth, MC38 tumours are increasingly infiltrated by both anti-tumour TH1 effector and suppressive TREG CD4+ subsets." (PMID 37153625, 2023). "Immune cell composition in each cluster was further investigated using the ratio of neutrophils/T-cells (CD4+ and CD8+) across tumours." (PMID 37258531, 2023). "CRGC-B showed a tumor-infiltrating lymphocyte environment that was more conducive to immunotherapy, including extensive infiltration by CD8+ T cells and CD4+ T cells, as well as enrichment of M1/M2 macrophages." (PMID 37746284, 2023). "The interplay between tumor and immunity begins when tumor antigens are presented by dendritic cells and activate CD8+ T cells and CD4+ T cells to exert cytotoxic effects." (PMID 36911744, 2023). "We found that several protein biomarkers, most notably panCK, IDO1, CD44, and Ki-67, were expressed at higher levels in responders’ tumor compartments; however, in the stroma, SMA, Fibronectin, CD4, and CD27 were the most differentially expressed." (PMID 37153589, 2023). "Immunohistochemistry for CD4+, CD8+, and CD45+ was used for assessing tumor-infiltrating immune cells." (PMID 37761986, 2023). "CD4+ T cells are known to function through cytokines that help immune cells such as CD8+ T. However, CD4+CD25+ Treg cells, a subpopulation of CD4+ T cells, suppress effector T cells and thereby impair anti-tumor immunity." (PMID 36741965, 2023).
tumor (continued). "Enrichment of Tregs inhibits CD4 + T cells, CD8 + T cells, antigen-presenting cells (APCs), monocytes, and macrophages, allowing tumor cells to proliferate more rapidly under immunosuppressive conditions." (PMID 38066437, 2023). "TTFields treatment also significantly increased the proportion of CD4+ T cells and CD8+ T cell infiltration inside and around tumor metastases." (PMID 38067345, 2023). "Consistent with changes in the immune state in the tumour tissues, NIL-IM-Lip+PD-1+L activated more CD4+ T cells, CD8+ T cells and NK cells and inhibited more Treg cells in the LNs." (PMID 37076492, 2023). "The expression levels of TNF-α, IL-6, and IL12p70 were upregulated in vivo and in vitro, and the infiltration of immune CD4 and CD8 T cells was detected in tumor tissues under laser irradiation." (PMID 37896250, 2023). "Targeted RNA-Seq was performed on CD4+ and CD8+ T cells from digested NSCLC tumor tissue and single-cell RNA-Seq data was analyzed to investigate the functional significance of CD39+ T cell populations." (PMID 37648263, 2023). "TILs are pivotal components of the host immune response to tumor cells and include CD8+ T cells, CD4+ helper T cells, regulatory T cells, B cells, etc.." (PMID 37302081, 2023). "Together with reports from multiple immune vaccine studies that responses were primarily driven by CD4+ T cells, these findings place further emphasis on the central importance of MHC II for effective anti-tumor immune responses." (PMID 37173324, 2023). "Immunohistochemical staining targeted various T-cell markers (CD3, CD4, CD8, and FOXP3), T-cell exhaustion markers (TOX and TIGIT), a B-cell marker (CD20), and a neutrophil marker (CD66b) in tumor and tumor-free mucosa from both groups." (PMID 37835436, 2023). "Innate immune cells (e.g., macrophages, DC, and neutrophils) and adaptive immune cells (e.g., CD4 + T cells, CD8 + T cells, and B cells) are the most critical components of tumor immunity." (PMID 36545914, 2023). "Previous reports have shown that peripheral CD4+ and CD8+ T cells play antagonistic roles in skin carcinogenesis, wherein CD8+ T cells are protective against tumor development and CD4+ cells are pro-tumorigenic." (PMID 37175480, 2023). "In conclusion, the reanalysis of TNBC data revealed the functional differences between CD4+ and CD8+ T cells, with differential gene expression in tumor tissues before and after paclitaxel treatment." (PMID 37762493, 2023). "Specifically, the abundance of α-SMA+ CAFs correlated with CD163+ MØs, in addition, we observed significantly positive correlations among α-SMA+ CAFs, CD163+ MØs and anti-tumor immune cells (i.e. CTLA4, FOXP3, CD4 and CD8 T cells)." (PMID 37254126, 2023). "Professional antigen-presenting cells (APCs), such as DCs, process and present tumour antigens in complex with major histocompatibility class I and II molecules (MHC-I or MHC-II) for the stimulation of CD8 and CD4 T cells through TCR-mediated recognition." (PMID 38567060, 2023). "THF increased the levels of CD3+/CD4+ and CD3+/CD8+ T-cells in the tumor and TDLNs of the MC-38 and 4T1 tumor bearing mice." (PMID 37924094, 2023). "The COX-2-PGE2 pathway promotes tumor immune evasion by regulating myeloid-derived suppressor cells, lymphocytes (CD8+ T cells, CD4+ T cells and natural killer cells), and antigen presenting cells (macrophages and dendritic cells)." (PMID 36776289, 2023). "We next performed Nanostring nCounter gene expression analysis of sorted CD4+ and CD8+ T cells from NCL and tumor tissue from early untreated NSCLC patients to analyze the effect of the TME on the T cell transcriptome." (PMID 37648263, 2023). "In malignant melanoma, targeted inhibition of HIF-1α induced high levels of CCL2 and CCL5 expression and then increased the invasion of tumor-killing NK cells, CD3+, CD4+, and CD8+ T cells in tumor tissues." (PMID 36675491, 2023).